VRK1 (VRK serine/threonine kinase 1)
Diseases named in the same sentence as VRK1 in open-access papers (continued):
Sharing a sentence is not in itself a finding about the gene and the disease.
cancer (35 papers, 2008 to 2026). A tumor composed of atypical neoplastic, often pleomorphic cells that invade other tissues. "The cancer with the highest mutation frequency of VRK1 was UCEC, which exceeded 4% and mainly was the “Mutation” type." (PMID 38157278, 2023). "In this study, VRK1 was identified as a risk factor in 9 cancer types and a protective factor in 2 cancers." (PMID 38157278, 2023). "The results indicated that higher VRK1 expression was significantly associated with poorer survival outcomes in these cancers, namely ACC, KICH, LGG, and LIHC." (PMID 38157278, 2023). "Given the substantial prognostic significance of VRK1 in various cancers, we investigated to explore the underlying biological processes or pathways associated with VRK1, aiming to elucidate its potential mechanisms of action." (PMID 38157278, 2023). "According to the findings, the five MMR genes were associated with VRK1 in most cancer types except for CHOL and UCS." (PMID 38157278, 2023). "Moreover, by integrating ImmuneScore, EstimateScore, StromalScore, and neoantigen data, we observed that VRK1 was associated with immune infiltration in certain cancer types." (PMID 38157278, 2023). "Next, we explored the mutation landscape of VRK1 in various cancers." (PMID 38157278, 2023). "Although VRK1 has been considered a pro-proliferative kinase and overexpression is associated with a variety of cancers, it has been unclear how it might contribute to cancer initiation or progression." (PMID 30180179, 2018). "As an oncogenic driver, VRK1 expression is highly increased in several types of cancer, such as breast cancer, ovarian cancer, non-small cell lung cancer, head and neck squamous cell carcinomas, glioma and neuroblastomas." (PMID 40234378, 2025). "VRK1 is the most abundant nuclear kinase, is overexpressed in many types of cancer, and is involved in cell proliferation." (PMID 39202333, 2024). "The roles played by VRK1 in the context of several different nuclear functions can have important implications for the understanding of major diseases such as cancer and neurological diseases." (PMID 38753965, 2024). "In various cancers, VRK1 expression exhibited positive correlations with immune infiltrating cells, immune checkpoint-related genes, TMB, and MSI." (PMID 38157278, 2023). "Following the comprehensive pan-cancer analysis, we present essential insights into VRK1 across various cancer cohorts." (PMID 38157278, 2023). "A holistic approach considering the complex genetic landscape is imperative to unlock the full potential of VRK1 as a therapeutic target in cancer." (PMID 38157278, 2023). "Our study analyzed the expression patterns and predictive values of VRK1 in pan-cancer using multiple databases." (PMID 38157278, 2023). "In summary, our comprehensive pan-cancer analysis of VRK1 has revealed its potential as a valuable cancer prognosis biomarker." (PMID 38157278, 2023). "We investigate the correlation between VRK1 expression and multiple factors, including prognosis, enriched gene sets, immune cell infiltration, and expression of immune regulators on a pan-cancer level." (PMID 38157278, 2023). "Next, we evaluated the differential expression pattern of VRK1 in cancers and adjacent carcinoma tissues." (PMID 38157278, 2023). "To explore the functional implications of VRK1 expression, we identified differentially expressed genes (DEGs) between low- and high-VRK1 subgroups in each cancer." (PMID 38157278, 2023).
cancer (continued). "The expression level of the VRK1 gene was significantly higher in cancer tissues of LUSC patients than in paracancerous tissues." (PMID 37547297, 2023). "Our study revealed a significant correlation between immune infiltration in cancers and the expression of VRK1." (PMID 38157278, 2023). "Drawing from these data, we propose VRK1 as a novel and promising biomarker for predicting patient prognosis and gauging the potential effects of immunotherapy across various cancer types." (PMID 38157278, 2023). "By analyzing these large-scale datasets, we aimed to gain a comprehensive understanding of VRK1’s expression patterns in different cancers, shedding light on its potential roles and implications in cancer development and progression." (PMID 38157278, 2023). "By comparing the experimental results with the informatics analysis, we sought to strengthen the evidence supporting the dysregulation of VRK1 in cancer." (PMID 38157278, 2023). "The expression pattern, predictive value, and biological function of VRK1 in various cancers remain largely elusive and warrant further investigation." (PMID 38157278, 2023). "Altogether, our research sheds light on the multifaceted role of VRK1 in cancer and presents a promising avenue for future investigations and therapeutic advancements in the field of cancer treatment." (PMID 38157278, 2023). "We also observed the correlation between VRK1 expression and the pathological stages of cancers, including ACC, BRCA, CESC, KICH, LIHC, SKCM, LUSC, and STAD." (PMID 38157278, 2023). "The postoperative LUSC tissues and paracancerous tissues of 25 LUSC patients were collected for the detection of VRK1 mRNA expression, and the study showed that the VRK1 gene expression level in cancer tissues was higher than that in paracancerous tissues." (PMID 37547297, 2023). "We found that VRK1 expression was remarkably correlated with these four DNMTs in almost all cancers except in UCS." (PMID 38157278, 2023). "Nevertheless, this pan-cancer study provides a deeper understanding of the role of VRK1 in the functional nucleus of different tumors." (PMID 38157278, 2023). "We found that VRK1 was positively associated with the common lymphoid progenitor and MDSC in most TCGA cancers." (PMID 38157278, 2023). "This analysis involved the integration of multiple databases to obtain a holistic understanding of VRK1’s expression patterns in different cancer types." (PMID 38157278, 2023). "The results suggest a potential role for VRK1 in regulating the immune response in these cancer types." (PMID 38157278, 2023). "To gain further insights into the predictive potential of VRK1 in various cancers, we analyzed the prognostic indicators of 33 different cancer types using the Kaplan-Meier method and univariate Cox regression analysis." (PMID 38157278, 2023). "Using reverse transcription quantitative PCR and Western blotting, we found that VRK1 expression in cancer tissues is higher than that in adjacent tissues (p < 0.05)." (PMID 35559251, 2022). "VRK1 is a widely-detected gene, and its relationship with the cell cycle and cancer progression is relatively clear, which is helpful for the accuracy of our verification." (PMID 36052378, 2022). "Taken together, these studies suggest that targeting VRK1 in cancers that harbor VRK2 promoter–methylated is a potential therapeutic strategy." (PMID 36040810, 2022). "For VRK1 inhibition to be a viable therapy option, a significant therapeutic ratio is required where normal tissues are spared while cancer cells are targeted." (PMID 36040810, 2022). "Further data analysis found that the expression differences of VRK1 is not only in between the cancer and paracancerous tissues as described in the database but also in the clinical data we included, which related to the prognosis of patients." (PMID 35559251, 2022).
cancer (continued). "In line with these important roles of VRK1 during G1/S in cancer cell progression, accumulating evidence has suggested that HNRNP A1 is another critical regulator of cell cycle progression." (PMID 34071140, 2021). "VRK1 is widely expressed in proliferative tissues, including embryonic tissues, adult testis, and thymus, as well as in several cancer cell lines." (PMID 33852630, 2021). "In cancer progression, VRK1 promotes the G1/S transition through phosphorylating the cAMP response element (CRE)-binding protein (CREB), thereby enhancing the binding affinity of CREB to the cyclin D1 (CCND1) promoter." (PMID 34071140, 2021). "We found that HNRNP A1 was significantly overexpressed in tumors compared with normal tissues, but the upregulation of VRK1 expression in cancer was contradictory." (PMID 34071140, 2021). "The combined use of olaparib with VRK1 inhibitors can result in cancer treatments with less severe, or fewer, side effects and toxicity, and thus better tolerated." (PMID 31101118, 2019). "The combination of ionizing radiation with inhibitors of DNA damage responses increases the accumulation of DNA damage in cancer cells, which facilitates their antitumor effect, a process regulated by VRK1." (PMID 31101118, 2019). "VRK1 has been proposed to play a role in cancer progression by promoting the G1 to S cell cycle transition, in part by phosphorylating the CREB1 transcription factor and increasing Cyclin D1 mRNA levels." (PMID 30180179, 2018). "Knockdown of VRK1 sensitizes cells to other cancer treatments based on DNA damage such as ionizing radiation or doxorubicin by impairing the DNA damage response." (PMID 29679095, 2018). "These properties, in the context of cancer, can contribute to a poorer prognosis of tumors overexpressing VRK1 because of its contribution to the promotion of cell proliferation and resistance to treatments based on DNA damage." (PMID 29679095, 2018). "Up-regulation of VRK1 has been observed in various human cancers, and a high level of VRK1 at the protein or RNA level is associated with a proliferative phenotype." (PMID 29029460, 2017). "In breast cancer, VRK1 depletion can inhibit cancer cell proliferation in vitro as well as growth and metastasis in vivo." (PMID 29029460, 2017). "For example, high levels of VRK1 mRNA have been detected in actively proliferating cells within fetal tissues and in several cancer cell lines." (PMID 26375549, 2015). "Here, we evaluated the efficacy of luteolin as a VRK1-targeted inhibitor for developing an effective anti-cancer strategy." (PMID 25310002, 2014). "Facilitating DNA repair in DNA-damage based treatments against cancer cells can contribute to a poorer prognosis of tumors with high levels of VRK1." (PMID 24731990, 2014). "Diagnostic values of VRK1 and BANF1 in various cancers were assessed using ROC analysis." (PMID 40384864, 2025). "In conclusion, these findings suggested that VRK1/CHD1L/SNAI1 axis acts as a cancer-driving pathway to promote the proliferation and EMT of HCC, indicating that targeting VRK1 may be an attractive therapeutic strategy of HCC." (PMID 40234378, 2025). "VRK1 depletion or inhibition has an important effect on epigenetic posttranslational modifications of histones, and as an indirect epigenetic modifier, is also a potential target for the development of novel therapeutic combinations in cancer." (PMID 38753965, 2024). "Depletion of VRK1 sensitizes cells to genotoxic cancer treatments." (PMID 38753965, 2024). "Therefore, targeting VRK1 in combination with histone epigenetic inhibitors can lead to novel synthetic lethality strategies in cancer treatment." (PMID 38732093, 2024). "The findings suggest that VRK1 may have played a crucial role in advancing and predicting cancer through its interaction with the microenvironments associated with the disease." (PMID 38157278, 2023). "These research findings contribute to a deeper understanding of VRK1, in the development of cancer." (PMID 38157278, 2023).
cancer (continued). "Additionally, the correlation analysis conducted between VRK1 and the pan-cancer immunomodulatory factors indicates a strong correlation between VRK1 expression and the expression of immunomodulatory genes, particularly in LIHC and THYM." (PMID 38157278, 2023). "We examined the frequency and types of genetic alterations of VRK1 in various cancer types." (PMID 38157278, 2023). "Furthermore, we observed that genetic alterations of VRK1 co-occurred with the frequency and pattern of these same genes, suggesting a functional partnership between VRK1 and these genes in the oncogenic processes across various cancer types." (PMID 38157278, 2023). "Our findings revealed that VRK1 expression was markedly upregulated in a majority of cancers." (PMID 38157278, 2023). "These experimental approaches allowed us to confirm whether VRK1 protein levels were indeed aberrantly expressed in cancer samples." (PMID 38157278, 2023). "Overall, VRK1 mRNA levels were abnormal in various cancer types." (PMID 38157278, 2023). "Hence, by analyzing the co-occurrence of gene expression and alterations, we have identified potential functional partners of VRK1 in cancer." (PMID 38157278, 2023). "Moreover, the high frequency and consistent pattern of co-occurring genetic alterations in these genes strongly suggests their involvement as functional partners in the oncogenic role of VRK1 in various cancers." (PMID 38157278, 2023). "Thus, while VRK1 holds promise as a target for cancer therapy, considering its interactions with other genes and pathways will be essential to develop effective and comprehensive treatment strategies." (PMID 38157278, 2023). "In addition, our study aimed to delve into the specific biological functions of VRK1 in cancer through in vitro experiments." (PMID 38157278, 2023). "Thus, we determined our research molecule VRK1, and verified in the TCGA database that the expression of VRK1 in cancer tissues is higher than that in paracancerous tissues." (PMID 35559251, 2022). "To identify genes or pathways that predict VRK1 dependency, we correlated gene expression data from the Cancer Cell Line Encyclopedia (CCLE) with VRK1 dependency and found that it was most strongly correlated with the loss of expression of its paralog VRK2 (Pearson correlation = 0.37, q < 10–25)." (PMID 36040810, 2022). "Given that the level of VRK1 is upregulated in several cancer cells and tissues, we checked whether VRK1 is upregulated at the transcript level." (PMID 34071140, 2021). "In addition, VRK1 is overexpressed in many cancer types and its correlation with poor prognosis has been determined, showing VRK1 as a new therapeutic target in oncology." (PMID 34067799, 2021). "These preliminary results suggest that our aptamers are specific inhibitors of VRK1 that might be used in cancer treatments." (PMID 34067799, 2021). "Additionally, VRK1 plays an essential role in cancer progression by controlling the cell cycle regulators associated with G1/S transition." (PMID 34071140, 2021). "Vaccinia-related kinase 1 (VRK1) has previously been identified as a cancer-related gene." (PMID 29029460, 2017). "Recent studies have uncovered the role of VRK1 in cell proliferation and cancer." (PMID 29029460, 2017). "Emerging evidence suggests VRK1 plays an essential role in cancer progression." (PMID 26375549, 2015). "In addition, luteolin regulates cell cycle progression by modulating VRK1 activity, leading to the suppression of cancer cell proliferation and the induction of apoptosis." (PMID 25310002, 2014). "VRK1 is potential target kinase for development of new specific inhibitors which can facilitate sensitization to other treatments in combination therapies; or alternatively be used as a new cancer drugs." (PMID 24731990, 2014). "Although it is reported that some drugs to inhibit other protein kinases might inhibit the kinase activity of VRK1, the inhibitory mechanism and anti-cancer effects through VRK1 inhibition were still elusive." (PMID 25310002, 2014).
cancer (continued). "Thus, considering the cell cycle-related characteristics of VRK1, the identification of VRK1 inhibitor is required for anti-cancer therapies." (PMID 25310002, 2014). "Therefore, we suggest that luteolin is an inhibitor of VRK1, which is one of good candidates to treat cancer." (PMID 25310002, 2014). "Development of specific inhibitors for VRK1 is highly likely and they might be very useful for cancer treatment in two ways." (PMID 24731990, 2014). "Both VRK1 and VRK2 proteins have been associated with the proliferation phenotype in carcinomas." (PMID 24079673, 2013). "Notably, some cancer types were observed only to have one kind of VRK1 genetic alteration." (PMID 38157278, 2023). "Thus, the findings indicated that VRK1 might interact with immune cells to influence cancer emergence, prognosis, and treatment." (PMID 38157278, 2023). "Consequently, VRK1 emerges as an appealing candidate for potential cancer therapies." (PMID 38157278, 2023). "Together, VRK1 could serve as a promising prognostic marker for cancer patients." (PMID 38157278, 2023). "Given the extensive involvement of VRK1 in a number of important biological processes such as cell cycle regulation, DNA repair, apoptosis and transcriptional regulation, the study of VRK1 in disease development and pan-cancer has attracted extensive attention in recent years." (PMID 38157278, 2023). "Consequently, these critical roles suggest that VRK1 could be an excellent candidate for cancer therapy and recent works have focused on VRK1 as a possible drug target for cancer treatment." (PMID 34071140, 2021). "Importantly, the existence of translation enhancement in the 3′UTR of VRK1 mRNA may have a significant meaning in the differential patterns of VRK1 gene expression in cancer cells." (PMID 34071140, 2021). "In most cell types, the human VRK1 gene is expressed at different levels and is not mutated in cancer, and it is overexpressed in many cancer types of different origins correlating with a poorer prognosis in breast, lung, liver, glioblastoma, head and neck, and esophageal cancer." (PMID 29679095, 2018). "Therefore, our study suggests that luteolin-induced VRK1 inhibition may contribute to establish a novel cell cycle-targeted strategy for anti-cancer therapy." (PMID 25310002, 2014). "Hence, we provide evidence supporting the notion that molecular targeting of VRK1 may contribute to the development of a strategy for alternative anti-cancer chemotherapy." (PMID 25310002, 2014). "Promoter methylation analysis revealed that VRK1 exhibited hypermethylation in BRCA, COAD, and KIRP, suggesting potential epigenetic regulation of VRK1 in these particular cancer types." (PMID 38157278, 2023). "A degrader strategy, as modeled in this current study, may represent an alternative approach to targeting VRK1 as a growing number of small molecule degraders (e.g., PROTACs, molecular glues, etc.)targeting specific proteins are undergoing clinical trials in diverse cancers." (PMID 36040810, 2022). "We conclude that VRK2 promoter methylation is observable among cancer subtypes and is a predictor for VRK2 expression and thus a VRK1 dependency." (PMID 36040810, 2022).